MTM1 (myotubularin 1)
Diseases named in the same sentence as MTM1 in open-access papers (continued):
Sharing a sentence is not in itself a finding about the gene and the disease.
X-linked myotubular myopathy (61 papers, 2008 to 2026). "Among them, X-linked myotubular myopathy is caused by MTM1 mutations, which lead to pathological PI3P accumulation, impaired autophagy, and muscle atrophy." (PMID 40869293, 2025). "Studies in X-linked myotubular myopathy animal models have demonstrated that loss of MTM1 results in PI3P accumulation in muscle." (PMID 39952567, 2025). "Mutations in their metabolizing enzymes are implicated in several pathologies, including X-linked myotubular myopathy, a severe myopathy caused by mutations in the MTM1 gene." (PMID 39952567, 2025). "MTM1-associated myopathy (also known as X-linked myotubular myopathy) is a rare disorder caused by a mutation in the MTM1 gene." (PMID 40869293, 2025). "Mtm1 p.R69C knock-in mice, which model the human phenotype of X-linked myotubular myopathy, were treated with ActRIIB-Fc." (PMID 40869293, 2025). "For instance, MTM1 is highly expressed in the membrane of platelets and utilized in the diagnosis of X-linked myotubular myopathy (XMLM)." (PMID 38529329, 2024). "X-linked myotubular myopathy is a defect in the MTM1 gene that causes skeletal muscle weakness in 80% of affected boys, and without intervention, greater than 50% of these children will die within the first 18 months of life." (PMID 38256124, 2024). "The ASPIRO trial enrolled 24 boys with X-linked myotubular myopathy who were on mechanical ventilatory support for treatment with an AAV8 delivering the human MTM1 transgene (1.3–3 × 1014 vg/kg)." (PMID 38256124, 2024). "MTM1 is the most common causative gene for X-linked myotubular myopathy (XLMTM), characterized by progressive muscle atrophy and centronuclear abnormalities." (PMID 37848047, 2024). "X-linked myotubular myopathy (XLMTM) is a fatal congenital disorder caused by mutations in the MTM1 gene." (PMID 37490339, 2023). "This study presents a case of X-linked myotubular myopathy in a female carrier of a pathogenic c.1261-10A>G variant in the MTM1 gene." (PMID 37176116, 2023). "Because de novo variants in CSNK2B have been reported to cause intellectual disability and epilepsy, while MTM1 has been linked to X-linked myotubular myopathy, we considered CSNK2B more interesting to investigate its contribution to the disease." (PMID 35571680, 2022). "In a study in mice models (Mtm1-KO) with X-linked myotubular myopathy, Maani and co-workers showed significantly prolonged survival and enhancement of muscle strength following treatment with TAM." (PMID 36467064, 2022). "X-linked myotubular myopathy (XLMTM) is a severe congenital myopathy caused by pathogenic variants in the myotubularin 1 (MTM1) gene." (PMID 35052449, 2022). "In contrast, in case 19, a hemizygous frameshift pathogenic variant of the MTM1 gene (NM_000252: c.1446_1447delTG, p.C482*) was identified, causing X-linked myotubular myopathy." (PMID 32411386, 2020). "X-linked myotubular myopathy (XLMTM) is a life-threatening skeletal muscle disease caused by mutations in the MTM1 gene." (PMID 33076971, 2020). "X-linked myotubular myopathy is associated with mutations in MTM1, which encodes myotubularin, a 603-amino acid phosphatidylinositol 3-phosphate (PI3P) phosphatase." (PMID 29141652, 2017). "Although the clinical presentations and histopathology were similar, the MTM1 p.(Q384P) mutation is different from the p.(N155K) mutation in exon 7 affecting Labrador retrievers with X-linked myotubular myopathy." (PMID 25664165, 2015). "The founding family member, MTM1, was discovered through genetic studies that revealed an association with X-linked myotubular myopathy." (PMID 25479419, 2014). "X-linked myotubular myopathy (XLMTM) is a congenital disorder caused by mutations of the MTM1 gene that encodes myotubularin." (PMID 23818870, 2013).
X-linked myotubular myopathy (continued). "Despite the safety of this approach, a recent phase I/II clinical trial (NCT03199469) for X-linked myotubular myopathy (MTM) utilizing AAV8 dose escalation of MTM1 protein (AT132) observed detrimental hepatic outcomes in humans when high viral loads (1 × 1014 vg/kg up to 3 × 1014 vg/kg) were used." (PMID 34981776, 2022). "In human, mutations in MTM1 are responsible for the X-linked myotubular myopathy." (PMID 36436378, 2022). "Myopathy due to MTM1 mutations is also known as X-linked centronuclear myopathy (CNMX)." (PMID 33827624, 2021). "Outside the use of gene therapy for hematological diseases, the role of preexisting liver disease has also been emphasized in the context of a clinical trial evaluating AT132 (an AAV8 vector containing a functional copy of the MTM1 gene) in patients with X-linked myotubular myopathy (XLMTM)." (PMID 35126126, 2021). "The major source of PtdIns5P in human cells comes from the action of the myotubularins, a family of phosphoinositide 3-phosphatases associated to different diseases: X-linked centronuclear myopathy (MTM1), Charcot-Marie-Tooth CMT4B1 (MTMR2), CMT4B2 (MTMR13) and CMT4B3 (MTMR5)." (PMID 28294977, 2017). "Indeed, mutations in the gene coding for the lipid phosphatase MTM1 cause X-linked myotubular myopathy (XLMTM), also known as centronuclear myopathy, likely by deregulating PtdIns3P metabolism." (PMID 28294977, 2017). "A neonatal onset of the disease, as further corroborated by our investigations, in a male newborn should be sufficient to lead clinicians toward a hypothesis of an X-linked myotubular myopathy and to request a direct MTM1 analysis." (PMID 27017278, 2016). "Here we describe a second pathogenic mutation in MTM1 causing X-linked myotubular myopathy in dogs." (PMID 25664165, 2015). "X-linked myotubular myopathy (XLMTM) due to MTM1 mutations is a rare and often lethal congenital myopathy." (PMID 41196692, 2025). "X-linked myotubular myopathy (XLMTM) results from mutations in myotubularin (MTM1), a phosphoinositide phosphatase important for myocyte homeostasis, including autophagy and vesicular transport." (PMID 40268053, 2025). "X-linked myotubular myopathy (XLMTM) is a rare neuromuscular disorder caused by loss-of-function mutation in the MTM1 gene." (PMID 35844027, 2022). "X-linked myotubular myopathy (XLMTM) is a rare congenital myopathy resulting from pathogenic variants in the MTM1 gene." (PMID 34641930, 2021). "Mutations in the MTM1 gene cause X-linked myotubular myopathy (XLMTM), characterized by neonatal hypotonia and respiratory failure, and are responsible for a premature mortality in affected males." (PMID 27017278, 2016). "An important, well-defined sub-group of CNMs is X-linked myotubular myopathy (XLMTM) associated with mutations in the MTM1 gene." (PMID 25664165, 2015). "For example, mutations in MTM1, the founding member of this family, cause X-linked myotubular myopathy (XLMTM), a severe congenital muscular disorder, while mutations in MTMR2 and MTMR13 are associated with Charcot-Marie-Tooth disease." (PMID 23114011, 2012). "For example, mutations in MTM1, the founder member of this family, cause X-linked myotubular myopathy (XLMTM), a severe congenital muscular disorder." (PMID 19816564, 2009). "X-linked myotubular myopathy (XLMTM) is a rare genetic disorder that typically presents at birth with progressive muscle weakness and respiratory difficulties and is caused by myotubularin-1 (MTM1) gene mutations." (PMID 41955018, 2026). "An example of such disease is X-linked myotubular myopathy (XLMTM), a severe muscle disorder characterized by muscle weakness and atrophy, which is due to mutations in the MTM1 gene." (PMID 39952567, 2025). "The interaction between MTM1 and MTMR12 is essential for the stability of functional protein complexes in skeletal muscle, which offers novel targets for Mtm1 mutation-induced X-linked myotubular myopathy (XLMTM)." (PMID 38529329, 2024).
X-linked myotubular myopathy (continued). "In X-linked myotubular myopathy (XLMTM), mutations of the MTM1 gene that encodes myotubularin protein lead to myotubularin deficiency and a rare, life-threatening congenital myopathy with estimated incidence of 1 in 40,000–50,000 newborn males." (PMID 37280644, 2023). "X-linked myotubular myopathy (XLMTM, OMIM #310400) is a rare congenital myopathy resulting from pathogenic variants in the MTM1 gene." (PMID 34641930, 2021). "Mutations in MTM1 cause X-linked Myotubular myopathy (XLMTM), a fatal congenital muscle disease." (PMID 32584877, 2020). "In addition, upregulation of dynamin 2 was observed in skeletal muscles from mtm1–/y mice, which accurately models human X-linked myotubular myopathy (XLCNM), and heterozygous knockdown of dynamin 2 in the mtm1–/y mouse improves muscle pathology and function." (PMID 26035394, 2015). "Loss-of-function mutations in MTM1 cause X-linked myotubular myopathy (XLMTM), a severe congenital myopathy with no available cure and a poorly understood pathomechanism." (PMID 41086017, 2025). "Each of these three CNVs contained one likely causative disease gene: SMCHD1, PMP22, or MTM1, involved in facioscapulohumeral muscular dystrophy-2 (digenic inheritence with the D4Z4 permissive haplotype), Charcot-Marie-Tooth disease 1A, and X-linked myotubular myopathy, respectively." (PMID 36781956, 2023). "The male newborn exhibited severe hypotonia and respiratory failure and was subsequently diagnosed with X-linked myotubular myopathy (XLMTM) via whole exome sequencing (WES), which identified a pathogenic myotubularin 1 (MTM1) gene mutation." (PMID 41328088, 2025). "Furthermore, three cases of severe hepatobiliary disease were recently documented in patients with X-linked myotubular myopathy (XLMTM), who received a high dose (3 × 1014 genome copies/kg) of AAV8 expressing the therapeutic MTM1 gene." (PMID 40508043, 2025). "X-linked myotubular myopathy (XLMTM) is a rare, life-threatening congenital myopathy arising from mutations in the MTM1 gene, resulting in an absent or dysfunctional myotubularin protein." (PMID 39285418, 2024).
congenital myopathy (21 papers, 2010 to 2026). "Type 1 myofiber predominance is also observed in other triadopathies, including RYR1, DNM2, BIN1 and MTM1-associated congenital myopathies." (PMID 39209426, 2024). "MTM1 mutations are associated with the X-linked myotubular myopathy-1, a congenital myopathy, with typical histological findings of central nuclei, hypotrophy and a predominance of type I fibers." (PMID 27017278, 2016). "The X-linked myotubular myopathy (XLMTM) also called X-linked centronuclear myopathy is a rare congenital myopathy due to mutations in the MTM1 gene encoding myotubularin." (PMID 24381816, 2013). "X-linked myotubular myopathy (XLMTM) is a subtype of congenital myopathy that predominantly affects males and is caused by mutations in the myotubularin (MTM1) gene." (PMID 23818870, 2013). "Myotubularin (MTM1, NM_000252) is a 3-phosphoinositides phosphatase mutated in a severe form of congenital myopathies called X-linked centronuclear myopathy or myotubular myopathy." (PMID 20140253, 2010). "Variants in MTM1 are associated with X‐linked myotubular myopathy (OMIM 310400), a congenital muscle disorder, which can cause severe congenital myopathy and early mortality." (PMID 30047259, 2018). "This differs from the defects of calcium handling already shown in other congenital myopathies including disorders linked to BIN1, RYR1 or MTM1 mutations that are centered on defects of triad membrane components, i.e. T-tubules and SR." (PMID 27870637, 2016). "Mutations in MTM1 result in XLMTM, which is a congenital myopathy that primarily affects the skeletal muscles in human patients and animal models." (PMID 23818870, 2013). "MTM1 is primarily involved with congenital myopathies through phosphatidylinositol signaling." (PMID 34528736, 2021). "Similarly, patient WES31 and WES67 had adult onset disease due to mutations in genes typically associated with congenital myopathies (MEGF10 and MTM1 respectively)." (PMID 28877744, 2017).
nemaline myopathy (3 papers, 2022 to 2025). Nemaline myopathy (NM) encompasses a large spectrum of myopathies characterized by hypotonia, weakness and depressed or absent deep tendon reflexes, with pathologic evidence of nemaline bodies (rods) on muscle biopsy. "The majority of these cases encompassed pathogenic RYR1 variants in core myopathy, NEB and ACTA1 in nemaline myopathy, and pathogenic MTM1 variants in CNM." (PMID 38982518, 2024). "In the present study, we investigated whether the expression of different groups of transcripts are similarly impacted in muscles from CM patients with AD and AR RYR1-related myopathies, SELENON-related MmD, KBTBD13-related nemaline myopathy and MTM1-related XL-MTM." (PMID 36196089, 2022). "Decreased RyR1 protein content has been reported in muscles from patients with AR RYR1 and SELENON-related MmD and MTM1-related XL-MTM19–23 but not in patients with nemaline myopathy." (PMID 36196089, 2022).
Skeletal myopathy (3 papers, 2011 to 2022). "While myotubularin is ubiquitously expressed, mutations within MTM1 lead to a skeletal muscle disorder: the X-linked form of centronuclear myopathy, also called myotubular myopathy, associating severe muscle atrophy and weakness at birth with abnormal positioning of nuclei." (PMID 21797990, 2011).
breast carcinoma (2 papers, 2018 to 2024). "Here, we show that tamoxifen, a well-known drug used against breast cancer, rescues the phenotype of Mtm1-deficient mice." (PMID 30451843, 2018). "Ubiquilin2 and myotubularin-1 recognize vimentin for degradation in skeletal muscle cells to avoid proteotoxic aggregate formation.In breast cancer, FERM domain-containing protein 3 (FRMD3) interacts with ubiquitin protein ligase E3A (UBE3A) to induce vimentin proteasomal degradation." (PMID 38383479, 2024).
cardiomyopathies (2 papers, 2021 to 2025). "Cardiac involvement was reported in one male patient in our cohort and not in female carriers, although cardiomyopathies have been previously also described in MTM1 carriers." (PMID 34463354, 2021).
Respiratory insufficiency (2 papers, 2021 to 2022). "Respiratory insufficiency was most frequently observed in male MTM1 patients, but occurred also in the other subgroups of CNM except for BIN1 patients." (PMID 34463354, 2021).
Stillbirth (2 papers, 2021 to 2026). Death of the fetus in utero after at least 22 weeks of gestation. "In 13% of the patients stillbirths in the family were reported; these were mainly MTM1 families." (PMID 34463354, 2021).
dilated cardiomyopathy (1 paper, 2021). Cardiomyopathy which is characterized by dilation and contractile dysfunction of the left and right ventricles. "Although MTM1’s role in t-tubule formation in cardiomyocytes is not yet resolved, PIs are indeed thought to be important for maintaining t-tubule integrity and MTM1 dysregulation can induce dilated cardiomyopathy." (PMID 34566684, 2021).
Diplopia (1 paper, 2021). Diplopia is a condition in which a single object is perceived as two images, it is also known as double vision. "Disturbed vision due to strabismus or diplopia was reported in 7 patients (15%), mainly in RYR1 and MTM1 patients." (PMID 34463354, 2021).
Ehlers-Danlos syndrome (1 paper, 2025). The Ehlers–Danlos syndromes (EDS) are a clinically and genetically heterogeneous group of heritable connective tissue disorders (HCTDs) characterized by joint hypermobility, skin hyperextensibility, and tissue fragility. "The analogy between MTM1 carrier status and Ehlers-Danlos syndrome is mechanistically plausible, as both hypothesize a pathway of compromised structural tissue integrity leading to uterine instability." (PMID 41328088, 2025).
liver disease (1 paper, 2023). "We uncovered a potential therapeutic strategy for MTM1-related liver disease (i.e., DNM2 inhibition) and set the groundwork for future investigation into MTM1 liver function and into factors and triggers that may modulate the cholestatic phenotype." (PMID 37490339, 2023).
Myalgia (1 paper, 2021). "Myalgia and cramps were reported by many BIN1 patients and female MTM1 carriers, while fatigue and exercise intolerance were common in all groups of CNM." (PMID 34463354, 2021).
neuropathy (1 paper, 2013). A disorder affecting the nervous system that manifests with pain, tingling, numbness, and/or muscle weakness. "On the basis of the ability of reduced FIG4 levels to rescue aspects of Mtmr2-dependent neuropathy, we evaluated the effect of Fig4 haploinsufficiency on the myopathy of Mtm1-knockout mice." (PMID 24004519, 2013). "In addition, we found that haploinsufficiency of Fig4 does not ameliorate effects of Mtm1 mutation in muscle, in contrast to a previous report that haploinsufficiency of Fig4 rescues the neuropathy associated with Mtmr2 mutation." (PMID 24004519, 2013). "However, in contrast to our findings in Mtm1-null mice, Bolino and colleagues found that plt haploinsufficiency rescued neuropathy in Mtmr2-knockout animals." (PMID 24004519, 2013).
osteosarcoma (1 paper, 2024). A usually aggressive malignant bone-forming mesenchymal neoplasm, predominantly affecting adolescents and young adults. "In osteosarcoma cells, the mRNA expression levels of MTM1 and MLH1 genes were significantly decreased, suggesting their functions may be inhibited in these cells." (PMID 39015570, 2024). "According to all experimental results, CLTCL1, MTM1, and MLH1 are likely tumor suppressor genes exerting inhibitory effects on osteosarcoma development, while SQLE and EDIL3 may function as targets promoting tumor proliferation, thus presenting new therapeutic potential." (PMID 39015570, 2024). "In comparison to osteosarcoma samples, the mRNA expression levels of the CLTCL1, MTM1, and MLH1 genes were significantly elevated in adjacent normal tissues (P=0.015, P=0.009, and P<0.001, respectively)." (PMID 39015570, 2024).
Polyhydramnios (1 paper, 2022). The presence of excess amniotic fluid in the uterus during pregnancy. "Analysis of the male fetal sample (case 1.4.1) revealed hemizygous VUS in MTM1 gene diagnosis of XR myotubular myopathy, which is associated with skeletal dysplasia and polyhydramnios in utero, both characteristics, were reported in the ultrasound report available." (PMID 35123515, 2022).
ptosis (1 paper, 2022). The drooping of the upper eyelid. "Mtm1−/yDnm2ex12b+/− mice appeared clearly more affected than Mtm1−/y mice as measured through a disease severity score assessing ptosis, kyphosis, breathing difficulties, position of hindlimbs when walking, ability to hang and difference of body weight." (PMID 36369230, 2022).
steatosis (1 paper, 2023). Increased lipid within the cytoplasm of cells. "Of note, we still observed increased Oil Red O staining, as well as dilation of the biliary tree, suggesting that the steatosis and dilated bile duct phenotypes may be driven by Mtm1 expression and function in cell types other than hepatocytes." (PMID 37490339, 2023).
Tetraparesis (1 paper, 2022). Weakness of all four limbs. "Spontaneous canine MTM1 and BIN1 models have previously been reported, and all recapitulated the human disorders at the clinical and histopathological level with severe muscle atrophy, swallowing difficulties and a rapidly progressive tetraparesis." (PMID 35244154, 2022).
X-linked adrenoleukodystrophy (1 paper, 2006). X-linked adrenoleukodystrophy (X-ALD) is a peroxisomal disorder resulting in cerebral demyelination, axonal dysfunction in the spinal cord leading to spastic paraplegia, adrenal insufficiency and in some cases testicular insufficiency.